LEP (leptin)
Diseases named in the same sentence as LEP in open-access papers (continued):
Sharing a sentence is not in itself a finding about the gene and the disease.
Barrett adenocarcinoma (1 paper, 2007). An adenocarcinoma arising from Barrett metaplastic epithelium in the esophagus. "Akt activation promotes proliferation and inhibits apoptosis in Barrett's adenocarcinoma cells and both transient acid exposure and leptin stimulate Akt phosphorylation." (PMID 17559672, 2007).
benign ovarian tumours (1 paper, 2017). "When comparing OC with benign ovarian tumours, six markers had statistically different expression (osteopontin, leptin, follistatin, PDGF-AB/BB, HGF, FGF-basic)." (PMID 28075407, 2017).
beta-thalassemia major (1 paper, 2015). Beta-thalassemia (BT) major is a severe early-onset form of BT characterized by severe anemia requiring regular red blood cell transfusions. "Based on Noori, it can be concluded that leptin’s change is independent from troponin, which is related to the cardiac involvement and the age of cardiac involvement in patients with beta-thalassemia major is 10–15 years." (PMID 25914798, 2015).
Borderline personality disorder (1 paper, 2025). A personality disorder characterized by impulsive behavior and unpredictable, capricious mood. "The associations between reduced leptin levels and higher frequencies of binge‐purging behaviours and comorbidity with borderline personality disorder, both characteristics highlighted in the maltreated eco‐phenotype, corroborate this hypothesis." (PMID 39643920, 2025).
breast cyst (1 paper, 2016). A fluid-filled closed cavity or sac that is lined by an EPITHELIUM and found in the BREAST. "So far there is the lack of experimental and clinical studies assessing the impact of leptin, adiponectin, and resistin on the risk of cancer development in women with breast cysts." (PMID 27293305, 2016). "The breast cyst fluid levels of leptin, adiponectin, and resistin were significantly decreased compared to plasma in both study groups." (PMID 27293305, 2016). "The last observation partially supports a hypothesis that leptin from the circulation may stimulate breast cysts development." (PMID 27293305, 2016). "Contrary to leptin, resistin, and adiponectin, IL-6 levels were similar and the levels of visfatin/NAMPT and TNF-α in breast cyst fluid were significantly greater than in the circulation in both study subgroups." (PMID 27293305, 2016). "It should be stressed that there is the lack of experimental studies assessing the role of leptin in oncogenic transformation of complex breast cysts." (PMID 27293305, 2016).
bronchiectasis (1 paper, 2018). Segmental, irreversible dilation of the bronchial tree resulting in the accumulation of secretions which leads to obstruction. "Candidate areas of research for the nodular-bronchiectasis MAC phenotype include leptin and ghrelin hormone influences on the immune response, cellular senescence, and the aging lung." (PMID 30559727, 2018).
burning mouth syndrome (1 paper, 2024). A condition characterized by a burning or tingling sensation on the lips, tongue, or entire mouth. "However, the variables being examined, such as body mass index (BMI), burning mouth syndrome (BMS), salivary flow rate (SFR), salivary leptin, salivary copper, and salivary magnesium, did not exhibit any significant variations in quantities between the diabetic and healthy groups (p > 0.05)." (PMID 39071038, 2024).
carbohydrate metabolism disorders (1 paper, 2021). "Significantly lower apelin concentration in women with PCOS (>5 fold) than in women without PCOS, associated with a concomitant increase in leptin, may also contribute to carbohydrate metabolism disorders occurring in the course of PCOS." (PMID 34604014, 2021).
cardioembolic stroke (1 paper, 2017). "If this relationship is proven, therapeutic interventions targeting the leptin level might represent a novel approach to reducing cardioembolic stroke incidence." (PMID 29225622, 2017).
cataract (1 paper, 2023). Partial or complete opacity of the crystalline lens of one or both eyes that decreases visual acuity and eventually results in blindness. "Nevertheless, studies showing that reduced blood levels of leptin lead to increased food intake and higher BMIs increase the risk of cataracts have already been published." (PMID 37892980, 2023). "Moreover, the leptin levels were positively correlated with the CRP levels in all cataract patients (r = 0.83, p = 0.011), including females (r = 0.95, p = 0.015)." (PMID 37892980, 2023).
cerebellar degeneration (1 paper, 2022). Degeneration of the cerebellum. "This has led some investigators to speculate that leptin resistance might also play a role in cerebellar degeneration, though our current understanding of the mechanistic processes by which this occurs is still in its infancy." (PMID 36204553, 2022).
cerebral small vessel disease (1 paper, 2025). Cerebral small vessel disease is the term currently used to pathological processes that affect the brain parenchymal circulation (arterioles, capillaries, and veins). "Recent cross‐sectional data on older men aged 50 years and over, with cerebral small vessel disease, found that in men higher leptin levels were associated with lower gray matter and total brain volumes." (PMID 39822062, 2025).
cervical (1 paper, 2012). "In-hospital death: in patients with cervical HF PTH (OR = 1.40; 95% CI 1.04-1.88; p = 0.027) and leptin (OR = 0.81; 95% CI 0.66-0.99; p = 0.040) and PTH (OR = 1.34; 95% CI 1.03-1.73; p = 0.027) in patients with trochanteric HF." (PMID 22333003, 2012).
childhood asthma (1 paper, 2018). "We hypothesized that the polymorphism in leptin (LEP) and leptin receptor (LEPR) genes is associated with childhood asthma and may affect their serum level." (PMID 30203371, 2018).
Chorangioma (1 paper, 2026). "Chorangioma-affected tissue harbored pathogenic COL1A1, FBXO11, and TRIM71 somatic mutations, with elevated Leptin expression and oxidative stress signatures." (PMID 41634840, 2026).
chorioamnionitis (1 paper, 2022). A morphologic finding indicating inflammation of the fetal sac membranes. "In summary, maternal diabetes and birth weight are associated with leptin while chorioamnionitis is associated with IL-6." (PMID 35197933, 2022). "Elevation in IL-6 levels is often found in cord blood of infants affected by maternal chorioamnionitis, suggesting leptin could be similarly impacted." (PMID 35197933, 2022). "Clinically diagnosed chorioamnionitis and neonatal sepsis were associated with increased IL-6 but not leptin." (PMID 35197933, 2022). "We hypothesized that there would be a positive correlation between IL-6 and leptin with progressively increased levels in pregnancies complicated by maternal diabetes and chorioamnionitis." (PMID 35197933, 2022). "The purpose of this study was to evaluate the association of two risk factors for impaired neonatal development, maternal diabetes and chorioamnionitis, with umbilical cord blood levels of two hormones that may contribute to long-term neurodevelopmental outcomes, leptin and IL-6." (PMID 35197933, 2022). "We utilized a high risk pregnancy cohort enriched with perinatal morbidities of interest to test the hypothesis that there is a positive correlation between cord blood IL-6 and leptin with progressively increased levels in pregnancies complicated by maternal diabetes and chorioamnionitis." (PMID 35197933, 2022). "Despite structural similarities and shared roles in inflammation, leptin and IL-6 have contrasting effects on neurodevelopment, and the relative importance of maternal diabetes or chorioamnionitis on fetal hormone exposure has not been defined." (PMID 35197933, 2022).
chronic graft versus host disease (1 paper, 2022). Chronic graft versus host disease (GVHD) is a complication that can occur after a stem cell or bone marrow transplant in which the newly transplanted donor cells attack the transplant recipient's body. "An elevation of Leptin was also described following alloSCT, particularly in those patients suffering from chronic graft versus host disease (cGvHD)." (PMID 35216457, 2022). "Multivariate Cox-regression analysis of pre-conditioning serum Leptin levels and known covariable revealed no significant influence on risk of mild (p = 0.373) or severe chronic GvHD (p = 0.721)." (PMID 35216457, 2022).
chronic kidney failure (1 paper, 2012). "In the general population leptin is considered an “appetite inhibitor”, however in contrast to preliminary findings, its role in chronic renal disease and hemodialysis patients is not completely found." (PMID 28197429, 2012).
cocaine addiction (1 paper, 2022). "Converging lines of evidence suggest that cocaine may alter leptin levels and that leptin may modulate cocaine addiction-like behaviors." (PMID 35316955, 2022). "A sub-hypothesis is that leptin may be a protective factor against the development of cocaine addiction-like behavior." (PMID 35316955, 2022). "In summary, these results demonstrate that high blood leptin level before access to cocaine may be a protective factor against the development of cocaine addiction-like behavior and that exogenous leptin reduces the motivation to take and seek cocaine." (PMID 35316955, 2022).
coronary stenosis (1 paper, 2023). Narrowing of the coronary artery lumen diameter. "In subgroup analysis, the level of leptin in EAT of CAD‐patients with local coronary stenosis near the right coronary artery ostium was significantly higher than those without." (PMID 37881786, 2023).
Delayed puberty (1 paper, 2016). Passing the age when puberty normally occurs with no physical or hormonal signs of the onset of puberty. "The mean serum leptin level was significantly lower in all patients with delayed puberty (P = 0.032)." (PMID 27088012, 2016).
demyelinating disease (1 paper, 2017). A broad group of disorders that affect the myelin sheaths that cover the neurons. "Therefore, we speculated that leptin treatment may be beneficial for treating demyelinating diseases." (PMID 28091609, 2017).
diabetic eye disease (1 paper, 2025). A group of disorders affecting the eye in patients with diabetes mellitus. "In the present study, intravitreal levels of leptin were also higher in PDR than in non-diabetic eye diseases (data not shown), further substantiating the involvement of leptin in the pathogenesis of DR." (PMID 41400317, 2025).
Duchenne muscular dystrophy (1 paper, 2025). Duchenne muscular dystrophy (DMD) is a neuromuscular disease characterized by rapidly progressive muscle weakness and wasting due to degeneration of skeletal, smooth and cardiac muscle. "A cross-sectional study with patients with Duchenne muscular dystrophy demonstrated that these patients had higher levels of leptin than the healthy individuals, but had reduced BMD and reduced bone turnover markers." (PMID 40076690, 2025).
dysautonomia (1 paper, 2025). An acute or chronic disorder, affecting the sympathetic or parasympathetic nervous system. "After a few months following injury, features of dysautonomia begin to resolve and at this point, it is possible that sympathetic inhibition of leptin signaling gives way to increase in leptin synthesis as observed after TBI unrelated to blast exposure." (PMID 40725107, 2025).
dystocia (1 paper, 2007). Slow or difficult obstetric labor or childbirth. "The increased cord blood leptin reported here with mild GDM in the Routine Care group, therefore suggests increased fetal fat deposition has occurred and may contribute to the fetal macrosomia and dystocia, as seen in GDM." (PMID 17430602, 2007).
edema (1 paper, 2020). An abnormal accumulation of fluid beneath the skin, or in one or more cavities of the body. "Plasma concentration of leptin is also increased following carrageenan‐induced rat paw edema." (PMID 32724582, 2020).
endometrioid endometrial carcinoma (1 paper, 2020). "Both FGF21 and leptin appear to be useful as a diagnostic, as well as showing a correlation with the degree of clinical and histopathological progress in patients with endometrioid endometrial carcinoma." (PMID 32570721, 2020).
energy metabolism disorder (1 paper, 2022). "Our results further substantiated the nonfunctional role of investigating LEP and LEPR genes as causative in a complex energy metabolism disorder." (PMID 35886710, 2022).
enteropathy (1 paper, 2022). "The direct association between enteropathy markers and leptin in the multivariate analysis may constitute further evidence that previously documented links between morbidity in early childhood and MetS in adulthood may be mediated by increased adiposity with EE as its etiology." (PMID 36096405, 2022).
esophagogastric junction adenocarcinoma (1 paper, 2019). "In this study, to acquire an understanding of the relationship between LEP polymorphism and risk of cancer, we first studied LEP G19A polymorphism with the susceptibility of developing esophagogastric junction adenocarcinoma (EGJA)." (PMID 30697798, 2019).
Failure to thrive (1 paper, 2022). Failure to thrive (FTT) refers to a child whose physical growth is substantially below the norm. "The reasons for failure to thrive are likely multifactorial, and may involve feeding difficulties, poor nutritional intake, hormonal abnormalities, increased resting energy expenditure, and dysregulated central control of body weight via leptin signaling in the hypothalamus." (PMID 35740842, 2022).
Follicular Cyst (1 paper, 2023). Cyst due to the occlusion of the duct of a follicle or small gland. "Firstly, follicular cyst follicles had extremely significant lower E2, insulin, IGF1 and leptin levels compared with normal follicles (p < 0.01)." (PMID 37958056, 2023). "The results showed that the follicular cysts were characterized by significant lower E2, insulin, IGF1 and leptin levels but elevated ACTH and ghrelin levels compared with normal follicles (p < 0.05)." (PMID 37958056, 2023).
follicular lymphoma (1 paper, 2005). Follicular lymphoma is a form of non-Hodgkin lymphoma characterized by a proliferation of B cells whose nodular structure of follicular architecture is preserved. "Findings varied with leptin genotype, the risks being decreased with LEP 19AA (OR=0.7, 95% CI 0.5–1.0) and increased with LEP −2548GA (OR=1.3, 95% CI 1.0–1.7) and −2548AA (OR=1.4, 95% CI 1.0–1.9), particularly for follicular lymphoma." (PMID 16160698, 2005).
fractures (1 paper, 2014). "Women with vertebral fractures have significantly lower plasma leptin levels but not fat mass percentage, and increased leptin levels have been suggested to be protective against nontraumatic fractures independent of body weight." (PMID 25140176, 2014).
galactosaemia (1 paper, 2018). "This study of galactosaemia has illustrated the dysregulation of glycosylation, inflammatory response and leptin metabolism as possible cellular event sequences with apoptosis in CG." (PMID 30231941, 2018). "The corresponding gene expression, the LEP gene and its receptor is significantly overexpressed in galactosaemia vs healthy controls (upregulated 8.88 fold, p < 0.01 and 6.38 fold, p < 0.001, respectively)." (PMID 30231941, 2018). "Circulating serum leptin data from both male and female galactosaemia cohorts were determined." (PMID 30231941, 2018). "From our earlier studies, we have suggested that abnormal N-glycosylation could putatively disrupt leptin-HPG signalling resulting from distorted Ob-r, soluble leptin receptor (sOb-R) and GnRH receptor (GnRH-R) function in galactosaemia." (PMID 30231941, 2018).
generalized anxiety disorder (1 paper, 2022). An anxiety disorder characterized by excessive and difficult-to-control worry about a number of life situations. "Interestingly, Salerno and colleagues examined the association of leptin levels and LEP rs3828942 with generalized anxiety disorder (GAD), taking into account gender differences." (PMID 35627229, 2022).
glucosuria (1 paper, 2022). "Empagliflozin administration (n = 8) only increased (P < 0.05) glucosuria and creatinine clearance and decreased (P < 0.05) plasma leptin and triglycerides concentrations in hypertensive rats." (PMID 35119333, 2022).
Gynecomastia (1 paper, 2024). Abnormal development of large mammary glands in males resulting in breast enlargement. "Leptin secreted by adipose tissue may play a role in the pathogenesis of pubertal gynecomastia." (PMID 39797240, 2024).
healthcare-associated infections (1 paper, 2022). "We aimed to determine whether serum leptin levels are predictive of the occurrence of healthcare-associated infections (HAIs) in hospitalized older patients." (PMID 35011102, 2022).
Hepatosplenomegaly (1 paper, 2024). Simultaneous enlargement of the liver and spleen. "Together, these data show that 3xTg-AD mice develop increased peripheral adiposity, including increased body weight, peripheral fat and leptin levels, as well as hepatosplenomegaly." (PMID 38565895, 2024).
heroin addiction (1 paper, 2009). "As it was already observed under in vivo conditions where serum leptin levels decreased in patients with heroin addiction, the consequences of modified leptin production during heroin consumption in pregnancy should be verified in further experiments." (PMID 19519880, 2009).
hidradenitis suppurativa (1 paper, 2020). A chronic suppurative and cicatricial disease of the apocrine glands occurring chiefly in the axillae in women and in the groin and anal regions in men. "On the other hand, it should be emphasized that enhanced local concentrations of leptin in subcutaneous adipose tissue could cause an intensification of the inflammatory response within the skin of patients with hidradenitis suppurativa." (PMID 33597945, 2020). "According to the latest results, an important relationship between leptin and hidradenitis suppurativa has begun to gain appreciation since leptin plays an important role in pro-inflammatory responses." (PMID 33597945, 2020). "Consistent with this notion, Malara and colleagues observed that serum levels of leptin were significantly increased in patients with hidradenitis suppurativa." (PMID 33597945, 2020).
hypertensive heart disease (1 paper, 2023). Abnormal enlargement of the heart resulting from long-standing hypertension. "Alterations in leptin concentrations are associated with CKD‐related cardiovascular problems such as hypertensive heart disease (HHD)." (PMID 36698704, 2023).
hypokalaemia (1 paper, 2023). "It has also been reported that leptin production triggers aldosterone secretion and may lead to secondary hypokalaemia." (PMID 37776262, 2023).
hypophosphatemia (1 paper, 2014). Lower than normal levels of phosphates in the circulating blood. "Treatment of HYP-mice with SPR4 peptide resulted in striking beneficial changes in serum glucose, insulin, leptin, osteocalcin, sclerostin, fat mass, 1.25(OH)2D3, and calcium with a partial correction of the hypophosphatemia." (PMID 24839967, 2014).
idiopathic nephrotic syndrome (1 paper, 2023). Nephrotic syndrome for which no cause has been identified. "In conclusion, this study has demonstrated an association between serum concentrations of CCL22 and Leptin, measured prior to steroid therapy, and steroid resistance in childhood idiopathic nephrotic syndrome." (PMID 37744450, 2023). "The present study focused on the serum concentrations of CCL22 and Leptin in patients with idiopathic nephrotic syndrome." (PMID 37744450, 2023).
iron overload (1 paper, 2016). "However, other reports mentioned that other factors can affect serum leptin levels, including lifestyle variables, serum lipid patterns, and iron overload." (PMID 27088012, 2016).